RNU6-611P (RNA, U6 small nuclear 611, pseudogene)
Gene: Small nuclear RNA gene on chromosome 19 (45,047,458 to 45,047,561, forward strand). Ensembl gene ENSG00000207003.
Homologues: Orthologues: chimpanzee U6 (98% identical), dog U6 (79% identical), guinea pig U6 (79% identical), pig U6 (79% identical), rat LOC120096367 (69% identical). Paralogues in human: RNU6-12P (89% identical), RNU6-13P (89% identical), RNU6-15P (89% identical), RNU6-31P (89% identical), RNU6-32P (89% identical), RNU6-1 (88% identical), RNU6-17P (88% identical), RNU6-18P (88% identical), RNU6-19P (88% identical), RNU6-2 (88% identical), RNU6-3P (88% identical), RNU6-41P (88% identical), and 1289 more.